MRO (maestro)
Synonyms: B29; C18orf3; FLJ30140
Tractability: No criterion of Open Targets' tractability assessment is met for any kind of drug.
Gene: Protein-coding gene on chromosome 18 (50,795,120 to 50,825,449, reverse strand). Ensembl gene ENSG00000134042.
Subcellular location: Nucleus, nucleolus
Gene Ontology:
Cellular component: nucleolus
Genetic constraint (gnomAD): Loss-of-function variants: 24 observed, 23.57 expected, observed/expected ratio (o/e) 1.02, 90% interval 0.74 to 1.43. The upper end of that interval is the gene's LOEUF score, 1.43, which puts it in group 5 of 6, group 1 being the genes least tolerant of losing a copy. Missense variants: 321 observed, 287.21 expected, observed/expected ratio (o/e) 1.12, 90% interval 1.02 to 1.23. Synonymous variants: 105 observed, 109.04 expected, observed/expected ratio (o/e) 0.96, 90% interval 0.82 to 1.13.
Homologues: Orthologues: chimpanzee MRO (98% identical), macaque MRO (94% identical), rabbit MRO (83% identical), guinea pig MRO (81% identical), pig MRO (81% identical), dog MRO (75% identical), mouse Mro (74% identical), rat Mro (66% identical). Paralogues in human: MROH2B (37% identical), MROH2A (27% identical), MROH1 (26% identical), MROH5 (25% identical), MROH6 (19% identical), MROH7 (19% identical), MROH9 (17% identical), MROH8 (16% identical).
Diseases named in the same sentence as MRO in open-access papers:
MRO is named in the same sentence as 4 diseases in open-access papers, as found by Europe PMC text mining. Sharing a sentence is not in itself a finding about the gene and the disease. The quoted sentences say what the papers report.
Polycystic Ovarian Syndrome (3 papers, 2017 to 2022). "Previously, studying gene expression in human ovarian cumulus cells, we found increased expression of MRO in lean-type Polycystic Ovarian Syndrome (PCOS) subjects, as compared to controls." (PMID 28406912, 2017). "Expression of MRO in lean-type polycystic ovarian syndrome has been found to be increased." (PMID 36193505, 2022). "A recent study had found that MRO was also expressed abnormally in ovarian cumulus cells of polycystic ovaries, but its function in follicular maturation is unknown." (PMID 33391342, 2020).
thyroid cancer (1 paper, 2022). "Nevertheless, MRO has been poorly studied in the tumors, and the role of MRO in thyroid cancer has not been previously reported." (PMID 36193505, 2022).
MRO also shares sentences with these, for which no sentence is quoted: glioma (1 paper); ovarian carcinoma (1).